INS (insulin)
Diseases named in the same sentence as INS in open-access papers (continued):
Sharing a sentence is not in itself a finding about the gene and the disease.
diabetes (continued). "Diabetes mellitus (DM) is a disease characterized by disarrangements in carbohydrate, protein and lipid metabolism caused by the complete or relative insufficiency of insulin secretion and/or insulin action." (PMID 19840387, 2009). "Epidemiological and clinical studies suggest a connection between diabetes, high insulin levels and cognitive impairment." (PMID 27713238, 2009). "These associations remained significant for insulin, HOMA-IR, HOMA2-IR, LDL and TCH among a subgroup of participants who were free of CVD and diabetes." (PMID 19426521, 2009). "Exogenous GLP-1 stimulates insulin secretion and individuals with diabetics have lower levels of GLP-1 secretion." (PMID 19835582, 2009). "We observed that insulin treatment brought back the decreased maximal velocity (Vmax) of acetylcholine esterase in the corpus striatum during diabetes to near control state." (PMID 19344500, 2009). "Type 2 diabetes mellitus is characterized by insufficient insulin secretion in response to elevations of plasma glucose." (PMID 19945403, 2009). "The major T-allele of the intronic JAZF1 rs864745 conferring increased diabetes risk was associated with increased 2nd phase serum insulin release during an IVGTT (p = 0.03), and an increased fasting serum insulin level (p = 0.001)." (PMID 19789630, 2009). "Diabetes is a metabolic disease characterized by hyperglycemia due to defects in insulin production, insulin action, or both." (PMID 19435501, 2009). "Insulin is an effective treatment for achieving tight glycemic control and improving clinical outcomes in patients with diabetes." (PMID 19573240, 2009). "During pregnancy Somali origin newborns were diagnosed to have more asphyxia and Somali origin parturients to have more than others insulin treatment for diabetes." (PMID 19298682, 2009). "In a new study, Nils Paumann, Diego Walther, and colleagues show that serotonin plays a key role in controlling insulin secretion and that its absence leads to diabetes." (PMID 20076734, 2009). "Fifty patients with mild to moderate depressive symptoms (74% female, aged 57 ± 9 yrs, diabetes duration of 10 ± 8 yrs, BMI 31 ± 6 kg/m2, HbA1C 7.7% ± 1.4, 53% insulin treated) were randomly assigned to either an intervention or a control group." (PMID 19709404, 2009). "This study has shown that use of an Internet-based system to facilitate the management of diabetes in insulin pump users is feasible and well accepted by participants." (PMID 21821504, 2009). "PPAR-γ is the best characterized isoform mainly because it regulates serum glucose levels and insulin sensitivity, therefore being widely used in the treatment of diabetes." (PMID 27713238, 2009). "In Borough B, where we used practice diabetes registers, recruitment was much quicker but most patients on the register proved ineligible (because of insulin treatment, ischaemic heart disease, cerebrovascular disease, or other co-morbidity)." (PMID 19228402, 2009). "Effects on glycaemic control, quality of life, self-rated diabetes symptoms, body composition, blood pressure, lipids, insulin resistance, beta-cell function and physical fitness will be examined after 6, 12 and 24 months." (PMID 19480671, 2009). "Given that diabetes is a progressive disease, the need for insulin in people with type 2 diabetes, will continue to rise." (PMID 19426530, 2009). "Using a published computer simulation model of diabetes we used UK-specific data to estimate the clinical consequences of immediately initiating insulin versus delaying initiation for periods in line with published estimates." (PMID 19804622, 2009). "We, however, report on a case of GSDIII with secondary diabetes successfully controlled with insulin." (PMID 19829878, 2009). "Plasma adiponectin levels are decreased in subjects with obesity and insulin resistance or type 2 diabetes mellitus, and are inversely correlated with visfatin and fasting insulin levels." (PMID 23675145, 2009).
diabetes (continued). "The lack of consensus about insulin initiation identified in this study calls for continuing medical education programmes that increase PCP knowledge about diabetes and the physiological effects of insulin." (PMID 18393965, 2008). "At least 50% of PCPs agreed that most of their patients on insulin are using their insulin as prescribed (item 14) and are satisfied with their diabetes therapy (item 16)." (PMID 18393965, 2008). "The glibenclamide-implanted mice progressively developed diabetes, lost the ability to secrete insulin in response to glucose and, after 1 wk of treatment, were as glucose intolerant as adult KATP knockout mice." (PMID 18959471, 2008). "In the present study persons with micro- or macroalbuminuria were more frequently treated with insulin alone or with insulin in combination with oral antidiabetic drugs in comparison to normoalbuminuric type 2 diabetes mellitus persons." (PMID 18986536, 2008). "In a partially closed-loop scheme of theinsulin-dependent diabetes therapy, measurements are conducted three to seventimes per day, and insulin injections are also performed three to four timesunder the supervision of a physician." (PMID 18566688, 2008). "The most striking observations of these investigations are that the UPS has a role in downregulating IRS proteins and thereby contributing to the two main defects in diabetes, insulin resistance and impaired insulin secretion." (PMID 19007436, 2008). "The results also indicated that diabetes specialists are less inclined than PCPs to delay insulin initiation." (PMID 18393965, 2008). "Insulin-dependent diabetes mellitus is a particular challenge, in that insulin drives potassium into cells, precipitating hypokalemia and an attack of paralysis." (PMID 18426576, 2008). "When approximately 80–90% of β-cells are destroyed, diabetes becomes clinically evident and patients require insulin replacement therapy." (PMID 19007436, 2008). "The alterations in metabolic function and insulin signaling in diabetes are reflected in the endothelial transcriptome's response." (PMID 18423039, 2008). "Our findings indicated that the combination of MES and HS alleviated insulin resistance and improved fat metabolism in diabetes mouse models, in part, by enhancing the insulin signaling pathway." (PMID 19114996, 2008). "Medical treatment of diabetes was achieved preoperatively with insulin in 14 patients from Group I versus 14 patients from Group II and with oral hypoglycemic agents in 27 patients from Group I versus 26 patients from Group II (p = 0.896)." (PMID 18573201, 2008). "Children had type 1 diabetes mellitus for > 1 year, had been treated with subcutaneous insulin for ≥ 2 months, and had a recent glycosylated hemoglobin (HbA1C) measurement." (PMID 18205937, 2008). "Daily self-management is related to daily diabetes activities such as administering insulin, exercising, and resting." (PMID 18366665, 2008). "A 68-year-old man with poorly controlled type 2 diabetes mellitus received different insulin preparations subcutaneously while on oral medication." (PMID 18727824, 2008). "Tolbutamide has long been used to treat diabetes and is known to act by stimulating insulin secretion through action on the pancreatic β-cells." (PMID 19902032, 2008). "Facts relating to 'type one' and 'type two' diabetes are mixed together, and the side effects of insulin are mixed up with the signs and symptoms of diabetes." (PMID 18789165, 2008). "One prerequisite for such tight control is accurate and frequent monitoring of the blood glucose level that provides useful information to guide a treatment plan (i.e., dosage of insulin or diabetes pill)." (PMID 27873829, 2008). "The risk of hypoglycaemia is increased in older patients, those with longer diabetes duration, lesser insulin reserve and perhaps in the drive for strict glycaemic control." (PMID 18215172, 2008).
diabetes (continued). "Both in vivo and in vitro studies of experimental diabetes report ICC depletion, perhaps secondary to loss of insulin/IGF and/or nitric oxide or other, as yet undetermined, survival factors." (PMID 18513423, 2008). "In fact,diabetes is a metabolic disease characterized by hyperglycaemia resulting from eitherdefects in insulin secretion or insulin properties, or both." (PMID 18604303, 2008). "Basically, in insulin-dependent diabetes therapies, control methods are classified into three categories: open-loop, closed-loop, and partially closed-loop controls." (PMID 18566688, 2008). "The hallmark of type 1 diabetes mellitus (T1DM) is selective destruction of beta-cells associated with severe or complete insulin deficiency, thereby making administration of exogenous insulin mandatory." (PMID 21264154, 2008). "The pathogenesis of diabetes in the GK rat involves an impaired insulin secretion, insulin resistance, an abnormal glucose metabolism as well as an impaired ontogenetic development of pancreatic islet cells and mitochondrial dysfunction in the liver and heart." (PMID 18523557, 2008). "The diagnosis of diabetes was made and the patient was started on rapid analog insulin subcutaneous, until her blood sugar was brought below 250 mg%, following which long-acting insulin was started and continued for the first day." (PMID 19116001, 2008). "Type 2 Diabetes Mellitus (T2DM) is a non insulin dependent, complex trait disease that develops due to genetic predisposition and environmental factors." (PMID 18605991, 2008). "The discovery, production, and clinical use of insulin in the 1920s greatly prolonged the life expectancy of patients with insulin-dependent diabetes mellitus." (PMID 19330070, 2008). "Diabetes mellitus is a chronic metabolic disorder relative to insulin deficit thatinduces metabolic and degenerative complications in various organs, including nerves,heart, and kidneys." (PMID 18509500, 2008). "Streptozotocin is a natural product that selectively kills insulin-secreting β cells, and is widely used to generate mouse models of diabetes or treat pancreatic tumors." (PMID 18721751, 2008). "Examples: An interactive diabetes simulation application is available for learning about how different insulin types interact with food intake and physical activity." (PMID 19040738, 2008). "Type 1 diabetes mellitus is characterized by an impaired ability to produce insulin due to the progressive and selective destruction of beta cells in the pancreatic islets of Langerhans." (PMID 18167535, 2008). "For example, insulin signaling regulates invertebrate and vertebrate lifespan, and drugs that target this pathway are central diabetes therapies." (PMID 18478054, 2008). "After constructing a mathematical model of the insulin-glucosedynamics, an insulin-dependent diabetes therapy is designed." (PMID 18437199, 2008). "The two types of diabetes are referred to as type 1 (insulin dependent) and type 2 (non-insulin dependent)." (PMID 21394262, 2008). "Diabetes first emerged around 2000 B.C. while insulin and its functionality were discovered in 1921." (PMID 18566688, 2008). "Insulin (as well as equipment and education) is a basic tool for survival for people with diabetes and is crucial to successful diabetes control strategies that can prevent costly complications down the road." (PMID 18284685, 2008). "This included using ACE inhibitors as first line for patients with diabetes who developed hypertension, increased use of aspirin, switching patients to glitazones, and conversion to insulin either directly or by referral to secondary care." (PMID 18205947, 2008). "Our finding of increased adiponectin (a molecule that can enhance insulin signaling) in our Type I model of diabetes contrasts with decreased adiponectin in human Type II diabetes." (PMID 18423039, 2008).
diabetes (continued). "Multivariable logistic regression analysis showed that EDN1 Asn/Asn was an independent protective factor for DR after adjustment for age, age at onset of diabetes and insulin therapy." (PMID 18806884, 2008). "Insulin stimulates NO production from endothelial cells, so people with diabetes usually have lower baseline levels of NO than do subjects without diabetes." (PMID 19079718, 2008). "Riddle noted that diabetes specialists tended to be more aggressive than primary care physicians (PCPs) with insulin initiation in patients with type 2 diabetes." (PMID 18393965, 2008). "The standard of care for many patients with Type 1 diabetes mellitus is currently exogenous insulin or insulin analog therapy." (PMID 18167535, 2008). "The extract has shown to possess glucose lowering activity and improve insulin sensitivity in animal models of type 2 diabetes mellitus." (PMID 21593982, 2008). "What is more, the use of structured SMBG appears to result in a significant reduction in HbA1c, even in individuals with non-insulin requiring diabetes." (PMID 19046192, 2008). "One hundred seventy seven (71%) of the patients were male and 87 (35%) patients had diabetes mellitus – 13 were receiving insulin at home, 59 oral hypoglycemic agents, 5 both, and 10 neither." (PMID 19025628, 2008). "In a study in Pima Indians, in which AST, ALT and GGT were measured at baseline, only ALT predicted diabetes after adjustment for age, sex, percent body fat and insulin sensitivity." (PMID 18533046, 2008). "Testing, insulin, and transport for a city dweller in Mali cost approximately $21.24 a month for diabetes care alone, or $225 a year, of which half, or $11 a month, would be reserved for just one vial of 100 IU insulin." (PMID 20165596, 2008). "Beta-cell dysfunction (hypersecretion and abnormal insulin processing) is manifest in the progression from normality to overt diabetes." (PMID 18516349, 2008). "The differences in DPN between the two types of diabetes are due to differences in the availability of insulin and C-peptide." (PMID 18437223, 2008). "In many countries, the cost of insulin and diabetes supplies far exceeds annual incomes, leaving people with diabetes unable to properly manage their condition, and susceptible to complications in the long-term." (PMID 18284685, 2008). "Although it is tempting to attribute sacral agenesis to alterations in carbohydrate metabolism induced by diabetes or exogenous insulin injections." (PMID 19099562, 2008). "In general, the closed-loop schemes of theinsulin-dependent diabetes therapy utilize an insulin pump that automaticallysupplies insulin into the human body subcutaneously." (PMID 18566688, 2008). "The EU developed telematic management of insulin dependent diabates mellitus(T-IDDM) which was a telemedicine system that supported clinician's decision-makingfor providing insulin for the insulin-dependent diabetics." (PMID 18566688, 2008). "Increased urinary TGF-β1 excretion was reported in patients with IgA nephropathy, nephritic patients with membranous nephropathy and in patients with insulin-dependent or- independent diabetes mellitus." (PMID 19468460, 2008). "These programmes should provide PCPs, especially those with large and challenging diabetes practices, with strategies and tools for successfully initiating insulin in patients with type 2 diabetes." (PMID 18393965, 2008). "In this diabetic model, the administration of 1,25D3 for 8 weeks was reported to improve diabetes attenuating pancreatic islet damage and decreasing the insulin requirements." (PMID 18638371, 2008). "Several barriers to insulin therapy are encountered by both the providers and the patients with type 2 diabetes mellitus." (PMID 19902051, 2008). "Rates of hypoglycaemia with insulin vary according to the regimen and the stage of evolution of the person's diabetes." (PMID 18215172, 2008).
diabetes (continued). "It has been suggested that protein transduction technology is useful for the treatment of diabetes, because this technology facilitates the differentiation of stem cells into insulin-producing cells." (PMID 18298656, 2008). "Diabetes specialists tend to be more aggressive than primary care physicians (PCPs) with insulin initiation in patients with type 2 diabetes, and US physicians are more disposed to delay insulin than physicians in other countries." (PMID 18393965, 2008). "Type 1 diabetes mellitus results from the progressive and specific autoimmune destruction of insulin-secreting pancreatic B-cells, which develops over a period of years and continues after the initial clinical presentation." (PMID 19046214, 2008). "Direct insulin signaling achieved by intrathecal administration of insulin reverses neuropathy in STZ-induced diabetes." (PMID 18312687, 2008). "Many of the chronic endothelial effects of diabetes will be reflected in transcriptional regulation, either as a direct response to hyperglycemia and abnormalities of insulin signaling, or as a secondary response to the effects of these stresses." (PMID 18423039, 2008). "In this paper, we survey blood glucose control schemes which lie onthe basics of the insulin-dependent diabetes therapies and systems." (PMID 18566688, 2008). "In patients with diabetes mellitus, subcutaneous administration of protamine-containing insulin preparations can also provoke delayed, T-cell mediated skin reactions or granulomatous hypersensitivity." (PMID 18727824, 2008). "Nonetheless, like other PPARagonists, treatment with bezafibrate significantly raises HDL cholesterollevels, reduces triglycerides, and improves insulin sensitivity in patientswith diabetes." (PMID 18288280, 2008). "The automated insulin dosage advisor (AIDA) is a virtual diabetes patient model that was originally designed for theeducational purpose so as to help patients and clinicians learn effectiveglycemic control." (PMID 18566688, 2008). "Diabetes mellitus is a metabolic disorder ofendogenous insulin allowing excessive amount of glucose to stay in blood." (PMID 18566688, 2008). "The United Kingdom Prospective Diabetes Study demonstrated the advantages of the early addition of insulin to conventional diet-plus-OAD treatment if the fasting plasma glucose (FPG) remained > 108 mg/dL despite maximal doses of sulfonylurea." (PMID 18279520, 2008). "Clinical practice guidelines recommend SMBG to both insulin and non insulin treated diabetes patients." (PMID 18501012, 2008). "Further studies on the role of SGK1 in human insulin secretion and diabetes onset are therefore needed." (PMID 18985156, 2008). "In United Kingdom Prospective Diabetes Study over 6 years, ~53% of patients will require addition of insulin therapy to achieve target HbA1C." (PMID 18577229, 2008). "The term LADA (latent autoimmune diabetes in adults) has been introduced to define adult diabetes patients who are initially non-insulin-requiring but with immune markers of type 1 diabetes, who progress to insulin dependency." (PMID 18652676, 2008). "The 3′ UTR is the target of mammalian microRNAs (miRNAs) and their relevance to diabetes is underscored by the finding that mouse islet-specific miR-375 affects insulin secretion." (PMID 18654634, 2008). "The presence of fibrillar protein deposits (amyloid) of human islet amyloid polypeptide (hIAPP) in the pancreatic islets of Langerhans is thought to be related to death of the insulin-producing islet β-cells in type 2 diabetes mellitus (DM2)." (PMID 18483616, 2008). "After three months ofsubstitution by both C-peptide and insulin, patients exhibited a better glycemic control,a reduction of diabetes-induced glomerular hyperfiltration and microalbuminuria." (PMID 18509500, 2008).